INS (insulin)
Diseases named in the same sentence as INS in open-access papers (continued):
Sharing a sentence is not in itself a finding about the gene and the disease.
Hyperglycemia (continued). "Though insulin and hyperglycemia are important regulators of the peripheral lymphocyte metabolism, unfortunately peripheral lymphocytes were not collected." (PMID 34940559, 2021). "T2DM is a metabolic disorder characterized by increased resistance to insulin in glucose-sensitive tissues and dyslipidemia leading to hyperglycemia, prolonged inflammation, and oxidative stress." (PMID 33748504, 2021). "Insufficient insulin production, often due to β-cell cytotoxicity or death, and resultant hyperglycemia are hallmarks of type 1 diabetes (T1D)." (PMID 34564296, 2021). "We obtained beta cells that not only secreted insulin under glucose stimulation in vitro but also ameliorated hyperglycemia in vivo." (PMID 34055806, 2021). "Long-term hyperglycemia can change the mechanism of arterial smooth muscle contraction through continuous insulin signaling." (PMID 34470604, 2021). "At 3–4 mo of age, male and female OZRs had excess weight gain with elevated plasma insulin and lipids, but only male OZRs had pronounced hyperglycemia with access to food." (PMID 33978481, 2021). "We reported that the effect of MG in reducing the insulin and C-peptide contents in serum, upregulating inflammatory cytokines, and inducing hyperglycemia in MG-administered rats previously." (PMID 34371651, 2021). "Our study’s strengths include well-matched cohorts, larger sample size than previous studies, insulin as the sole hyperglycemia medication, and availability of lispro doses at different meals with corresponding CBG data." (PMID 34529703, 2021). "Beneficial effects of dapagliflozin treatment on hyperglycaemia were primarily observed by improved glucose tolerance and decreased insulin plasma levels, but fasting blood glucose was unchanged." (PMID 34131781, 2021). "Insulin infusion was more frequent for both COVID-19 diagnosis and the presence of stress hyperglycemia." (PMID 34578888, 2021). "The leading antidiabetic drug is metformin, a plant derivative, which increases insulin sensitivity, reducing hyperglycaemia." (PMID 33440853, 2021). "The high content-release of essential amino acids, such as leucine, isoleucine, valine, lysine, and threonine, by LP after digestion, lead to increased secretion of insulin and decrease postprandial hyperglycaemia was verified." (PMID 34621771, 2021). "Our findings demonstrate that the brain, namely, the cortex, responds to insulin-induced recurrent hypoglycemia in the context of long-term hyperglycemia by evoking several adaptive metabolic responses." (PMID 34948265, 2021). "Pancreatic islet α- and β-cells are regulated by glucose concentrations, with hypoglycemia-triggering α-cells release glucagon and hyperglycemia-stimulating β-cells secret insulin." (PMID 34354571, 2021). "This would be reflected by faster or elevated counter-regulatory (i.e. insulin-antagonistic) responses to hypoglycaemia and, vice versa, by delayed or attenuated suppression of such responses during hyperglycaemia." (PMID 33241460, 2021). "The parameters and investigations used in the studies to determine insulin sensitivity were glucose disposal rates, hyperglycemia, and mean glucose uptake." (PMID 34790115, 2021). "Studies have shown that BMSC therapy improved insulin secretion, activate the insulin signaling pathway and enhance glucose transport, thereby reversing hyperglycemia in T2DM rats." (PMID 34722505, 2021). "This reduction in plasma insulin levels induced hyperglycemia and a significant increase in the levels of NEFAs in plasma." (PMID 34833964, 2021). "To summarize, the current evidence shows that LCN2 is involved in insulin sensitivity, glucose metabolism, vascular homeostasis, and hyperglycemia related to metabolic syndromes." (PMID 33945675, 2021).
Hyperglycemia (continued). "Taken together, the data presented here illustrate that insulin therapy may seem as more appropriate than other anti-DM pharmacotherapies in the management of COVID-19 patients with DM due to the lower risk of uncontrolled hyperglycemia and reduced propensity to develop diabetic ketoacidosis (DKA)." (PMID 34124187, 2021). "Hyperglycemia in women with GDM can be caused by the increased mechanisms of glycolysis/gluconeogenesis and by the inhibition of insulin signaling in peripheral tissues." (PMID 34681126, 2021). "Since insulin is a major anabolic hormone and glucose is a major anabolic fuel, the combination of hyperinsulinemia and hyperglycemia leads to an increase in fat and protein stores by the fetus." (PMID 33577577, 2021). "Many COVID-19 patients developed hyperglycemia due to critical illness and frequent glucocorticoid use or had diabetes as a comorbidity, requiring IV insulin infusion along with hourly glucose monitoring to prevent hypo- or hyperglycemia." (PMID 35855452, 2021). "Insulin treatment (NASH-STZ-HI vs NASH-STZ) impacted regulation of many of the same inflammation- and fibrosis-related pathways affected by hyperglycemia, however, with the majority of pathway-associated genes being downregulated." (PMID 33596938, 2021). "Global knockout mice were generated similarly by three different labs, which all reported similar pancreatic phenotypes: Hyperglycemia within the first week of life, reduced insulin expression, and early lethality (presumably due to hyperglycemia)." (PMID 34943978, 2021). "RXR agonists act as insulin sensitizers that decrease hyperglycemia, hypertriglyceridemia and hyperinsulinemia, suggesting an anti-diabetic effect in type-2 diabetic mouse models." (PMID 34680110, 2021). "In patients with MetS, elevated insulin levels led to an increase in serum fetuin-B levels, while hyperglycemia inhibited fetuin-B release." (PMID 34646426, 2021). "The patient also developed high fevers to 39.4 °C and severe hyperglycemia requiring a high dose insulin infusion with additional boluses of insulin for glucose levels exceeding 300 mg/dl." (PMID 34583724, 2021). "Common laboratory findings in NAFLD patients are hyperlipidemia, hyperglycemia, decreased insulin sensitivity, and mild or moderate elevations of liver enzymes, specifically, alanine and aspartate aminotransferases (ALT and AST)." (PMID 34950104, 2021). "Fasting glucose and insulin concentrations in the blood of ob/ob mice were significantly higher than those of WT mice, indicating that ob/ob mice exhibit the expected hyperglycemia and hyperinsulinemia." (PMID 33748705, 2021). "It is noteworthy to mention that hyperglycemia was observed in COVID-19 patients with mild and severe disease, despite insulin treatment." (PMID 34966381, 2021). "Over-reduction in insulin dosage in these patients would lead to significant hyperglycemia, and further dosage reduction should be avoided." (PMID 34434951, 2021). "We found that ZDF rats show spatial learning and memory impairment, therefore enabling us to confirm that the cognitive deficits are the result of T2DM phenotype (such as chronic hyperglycemia and insufficient insulin secretion)." (PMID 34485269, 2021). "Despite optimized insulin treatment combined with oral anti-diabetic drugs, severe hyperglycemia (from 200 to 300 mg/dL) persisted." (PMID 34281618, 2021). "Insulin replacement should mimic physiological patterns including baseline as well as bolus insulin for meals and in hyperglycaemia." (PMID 34684559, 2021). "Me inhibits catecholamine release, insulin secretion, and lipolysis in cats and induces hyperglycemia." (PMID 35106295, 2021). "In our patient series, fine-tuning of insulin doses allowed an overall normalization in glycemic average and a decrease of hyperglycemia 4 to 15 h after sports." (PMID 34512541, 2021).
Hyperglycemia (continued). "Two case reports have described spontaneous return to normal C-peptide levels and successful cessation of insulin therapy in patients with hyperglycaemia and positive islet autoantibodies." (PMID 34803927, 2021). "Both hyperglycemia and elevated free fatty acids induce CREM overexpression causing pancreatic B cell dysfunction by inhibiting insulin gene transcription and insulin secretion." (PMID 34205870, 2021). "Seven patients (4.2%) in the study group had hyperglycemia that required insulin administration, which was grade 3 (five patients) or grade 4 (two patients) according to the CTCAE criteria." (PMID 34640436, 2021). "The parasympathetic innervation of the islets potentiates insulin secretion during hyperglycemia through a cholinergic muscarinic mechanism." (PMID 34354571, 2021). "In contrast, our results from the perfused pancreas demonstrated that SSTR2a can increase insulin secretion during hyperglycemia." (PMID 33434183, 2021). "Continued high insulin secretion over many years can exhaust pancreatic β cells and deplete endogenous insulin altogether, necessitating early exogenous insulin therapy to control hyperglycemia." (PMID 33788827, 2021). "Rosmarinic acid ameliorates hyperglycemia and insulin sensitivity by modulating the expression of phosphoenolpyruvate carboxykinase and stimulating GLUT 4 expression in diabetic rats." (PMID 34394985, 2021). "Hyperglycemia ranged from 4% with ipatasertib to 92% with MK-2206, as insulin-mediated glucose homeostasis mainly relies on PI3K signaling." (PMID 34948307, 2021). "In the diabetic condition, hyperglycemia and hyperlipidemia led the lipid partitioning toward a metabolized or esterified state leading to an inhibition of the insulin signaling pathway and fat accumulation in the liver." (PMID 34204891, 2021). "Pramlintide, an analogue of amylin, can be co-injected with insulin to delay gastric emptying and suppress glucagon secretion and has been demonstrated to improve post-prandial hyperglycemia in T1D." (PMID 37745178, 2021). "Because of its rapid absorption and beginning of an action, intranasal insulin is equally effective as standard subcutaneous insulin in reducing postprandial hyperglycemia excursions." (PMID 34540446, 2021). "Accumulation of STZ in beta cells results in cell necrosis by DNA alkylating activity which in turn reduces the synthesis and release of insulin, responsible for hyperglycemia." (PMID 33881650, 2021). "Insulin infusion is the mainstay of therapy for treatment of hyperglycaemia in acute illness but what is the effect of insulin on the admixture of glucocorticoids and COVID-19?" (PMID 34220705, 2021). "The pdx1 mutant diabetic zebrafish genetically resembles human neonatal diabetes in that homozygous mutants show early onset, persistent hyperglycemia, along with reduced insulin and reduced β-cells." (PMID 34831487, 2021). "Biosynthetic short-acting insulin is often either Y-site administered or directly added into the parenteral nutrition admixture (PNA) in order to reduce hyperglycemia." (PMID 33801784, 2021). "It was also demonstrated that Dach1 is increased in the livers of obese mice and humans defecting insulin signaling, and thus promotes hyperglycemia and hyperinsulinemia state." (PMID 34681728, 2021). "Several reports have shown that defects in glucose-sensing machinery impair insulin secretion, leading to severe hyperglycemia." (PMID 34667273, 2021). "Oral PBA treatment started at 8 weeks of age, when Avy hIAPP mice already presented fasting hyperglycemia, glucose intolerance, and impaired insulin secretion." (PMID 34088954, 2021). "IGF-1 signaling, together with insulin/insulin receptor signaling, mediates cellular proliferation and survival in multiple pathological conditions including hyperglycemia." (PMID 34371877, 2021).
Hyperglycemia (continued). "Hyperglycemia was also attenuated in these mice with a concomitant increase in insulin production and an improved histological structure compared to mice in the PBS-treated group." (PMID 34926699, 2021). "Under conditions of hyperglycemia and hyperinsulinemia, the expression of miR-21 in glomerular endothelial cells depends on the relative concentrations of glucose and insulin." (PMID 33967958, 2021). "Due to impaired production and function of insulin, the circulating glucose level is increased, resulting in hyperglycemia and diabetic microvascular and macrovascular complications." (PMID 34946740, 2021). "In contrast, SSTR2 antagonism increased insulin during hyperglycemia as well as increased glucagon secretion during hypoglycemia." (PMID 33434183, 2021). "Hyperglycaemia is harmful to cells and can lead to an over expression of insulin independent glucose transporters (GLUT-1, GLUT-2, and GLUT 3), which leads to an increase in glucose uptake by endothelial, hepatic, immune, and nerve cells." (PMID 34368024, 2021). "Gene ontology analysis identified hypermethylation of genes related to cell fate commitment and regulation of insulin secretion in the hyperglycemia-treated VAL3." (PMID 34639069, 2021). "Atrophic changes in the cerebellum and frontal lobe and frontal white matter dysintegrity were correlated with chronic hyperglycemia and insulin resistance and worse performance in verbal memory recognition and executive function tests." (PMID 34777234, 2021). "PGC1α expression is repressed via the AKT pathway in response to insulin, and under GR activation, it participates to the onset of hyperglycemia, through inducing expression of hepatic neoglucogenic genes." (PMID 33435513, 2021). "Existing evidence indicates that correction of hyperglycemia with insulin therapy reduces hospital complications and decreases mortality in cardiac and general surgery patients." (PMID 34659435, 2021). "As insulin is the preferred medication for the treatment of hyperglycemia during pregnancy, the utilization of all oral antidiabetic agents decreased as pregnancy progressed, in line with an increase in the prescription of insulin." (PMID 33603191, 2021). "It demonstrated the disproportionate disease burden of T2DM and aggressive disease progression to the need for insulin therapy for hyperglycaemia management amongst younger children with T2DM who are morbidly obese and at‐risk minorities." (PMID 33855201, 2021). "Pancreatic β-cells produce more insulin in response to high blood glucose (hyperglycemia) resulting in hyperinsulinemia (high blood insulin), eventually leading to T2DM." (PMID 34349617, 2021). "MEM mice show characteristic hyperglycemia with a slightly higher weight and reduced capacity of insulin secretion from the pancreas in spite of overeating, similar to lean Asian patients with T2DM, as shown in a previous study." (PMID 34867790, 2021). "Canonically, insulin is thought of as an anti-inflammatory molecule, since insulin reduces hyperglycemia and thus decreases the oxidative stress and inflammation." (PMID 33800470, 2021). "T2D is characterized by insufficient insulin production by pancreatic beta cells in the face of peripheral insulin resistance, which results in chronic hyperglycemia." (PMID 35295132, 2021). "Obesity is associated with peripheral insulin resistance that requires increased insulin production to prevent the development of hyperglycemia." (PMID 33804882, 2021). "This condition is believed to develop when marked hyperglycemia is combined with supraphysiological amounts of insulin." (PMID 37465067, 2021). "When the extent of apoptosis due to repeated hyperglycemia exceeds the extent of regeneration of the pancreatic β-cell mass, the overall insulin secretion in response to a glycemic load is reduced, which results in more hyperglycemia." (PMID 34578968, 2021).
Hyperglycemia (continued). "In fact, FA increases gluconeogenesis, lipogenesis, and chronic inflammation, which foster hepatic glucose production, resulting in hyperglycemia and hepatic insulin resistance." (PMID 34141709, 2021). "Hyperglycemia, as one of the main symptoms for diagnosis, results from decreased insulin secretion and/or reduced insulin action and can lead to long-term damage and dysfunction of different organs." (PMID 34489694, 2021). "ID, the inability of pancreatic β-cells to secrete sufficient insulin in response to hyperglycemia, is the transition state from IR to T2DM." (PMID 33788827, 2021). "Administration of fructose and low dose of STZ causes partial disruption of the beta cells leading to less production of insulin and hence, hyperglycemia with insulin resistance." (PMID 33562428, 2021). "At E15, after six hours of fasting, the pregnant Igf2βKO mouse exhibited hyperglycaemia compared to pregnant controls, while fasting insulin levels remained comparable between the two genotypes." (PMID 33833312, 2021). "The major factor leading to hyperglycemia in lean T2D patients is impaired secretion of insulin from pancreatic β-cells." (PMID 34852897, 2021). "In the pathological conditions of GDM, insulin action is compromised and glucose uptake by these cells were disrupted, resulting in hyperglycemia." (PMID 34952629, 2021). "Symptoms manifested were hypoglycemia in 86.54%, recurrent episodes of symptomatic hypoglycemia in 35.58%, nocturnal hypoglycemia along with daytime hyperglycemia in 21.15% and recurrent hypoglycemia after discontinued insulin in 64.43%." (PMID 33827670, 2021). "For example, hyperglycaemia and hypoinsulinaemia or insulin end-organ resistance are known to impair WH via a reduction in dermal fibroblast proliferation and migration." (PMID 32572565, 2021). "It was lower in patients with stress hyperglycemia and in those in need for insulin infusion therapy (7.0 ± 4.7 vs. 12.3 ± 7.0 μg/L for subcutaneous insulin, t = 3.672, p = 0.001)." (PMID 34578888, 2021). "The postprandial hyperglycemia status is defined by factors, such as the timing, quantity, and composition of the meal, carbohydrate content of the meal, and the resulting insulin production and inhibition of glucagon secretion." (PMID 34203830, 2021). "Increases in PFNA concentration were found in reduced serum insulin, compromised ß-cell activity and pathological hyperglycemia in adolescents, whereas increased PFOS concentration was found in adults and positively associated with ß-cell activity." (PMID 34444092, 2021). "Collectively, while further study is needed, our data suggests that SC-secreted C-peptide along with insulin have beneficial effects in decreasing the hyperglycemia-induced endothelial dysfunction, activation, and oxidative stress." (PMID 33800470, 2021). "Improvement of hyperglycemia by insulin therapy however, has been found to negate the protective effects." (PMID 34820431, 2021). "The combination of lowered GLUT4 content and compromised insulin-stimulated GLUT4 translocation is suggested to lead to the postprandial hyperglycaemia and hyperinsulinaemia observed in the human homozygous TBC1D4 p.Arg684Ter variant carriers." (PMID 33912980, 2021). "Insulin resistance, an impaired response of the peripheral tissues to insulin, results in hyperglycemia, which is related to the development of type 2 diabetes (T2DM) and its complications, such as cardiovascular disease, retinopathy, and kidney failure." (PMID 34199668, 2021). "Pathophysiology of NODAT and PTDM differs from that of T2DM in that post-transplant hyperglycemia is considered to be a result of impaired insulin secretion by pancreatic beta-cells instead of reduced insulin sensitivity." (PMID 33808901, 2021). "Inorganic NO3− and NO2− improve glucose and insulin homeostasis in animal models of T2DM; supplementation with these anions decreases hyperglycemia and improves insulin sensitivity and glucose tolerance." (PMID 33947005, 2021).